EIF4G1 (eukaryotic translation initiation factor 4 gamma 1)
Description:
Component of the protein complex eIF4F, which is involved in the recognition of the mRNA cap, ATP-dependent unwinding of 5'-terminal secondary structure and recruitment of mRNA to the ribosome. Exists in two complexes, either with EIF1 or with EIF4E (mutually exclusive). Together with EIF1, is required for leaky scanning, in particular for avoiding cap-proximal start codon. Together with EIF4E, antagonizes the scanning promoted by EIF1-EIF4G1 and locates the start codon (through a TISU element) without scanning. As a member of the eIF4F complex, required for endoplasmic reticulum stress-induced ATF4 mRNA translation.
Synonyms: eIF-4G1; EIF4F; EIF4G; EIF4GI; p220; PARK18
Tractability: Small molecule: a structure with a bound ligand is known. PROTAC: ubiquitination databases record sites on it; its protein half-life has been measured.
Target class: Other nuclear protein
Gene: Protein-coding gene on chromosome 3 (184,314,490 to 184,335,358, forward strand). Ensembl gene ENSG00000114867.
Subcellular location: Cytoplasm; Nucleus; Cytoplasm, Stress granule
Subcellular location (Human Protein Atlas): Cytosol
Pathways (Reactome):
Metabolism of proteins: Activation of the mRNA upon binding of the cap-binding complex and eIFs, and subsequent binding to 43S; GTP hydrolysis and joining of the 60S ribosomal subunit; L13a-mediated translational silencing of Ceruloplasmin expression; Ribosomal scanning and start codon recognition; Translation initiation complex formation
Metabolism of RNA: AUF1 (hnRNP D0) binds and destabilizes mRNA; Deadenylation of mRNA; Nonsense Mediated Decay (NMD) enhanced by the Exon Junction Complex (EJC); Nonsense Mediated Decay (NMD) independent of the Exon Junction Complex (EJC)
Developmental Biology: M-decay: degradation of maternal mRNAs by maternally stored factors; Regulation of expression of SLITs and ROBOs; Z-decay: degradation of maternal mRNAs by zygotically expressed factors
Disease: Dengue Virus Genome Translation and Replication
Immune System: ISG15 antiviral mechanism
Signal Transduction: mTORC1-mediated signalling
Gene Ontology:
Molecular function: ATP binding; eukaryotic initiation factor 4E binding; mRNA binding; protein binding; RNA binding; translation factor activity, RNA binding; translation initiation factor activity; molecular adaptor activity; translation initiation factor binding
Biological process: cellular response to nutrient levels; energy homeostasis; miRNA-mediated gene silencing by inhibition of translation; negative regulation of autophagy; positive regulation of cell growth; positive regulation of eukaryotic translation initiation factor 4F complex assembly; positive regulation of G1/S transition of mitotic cell cycle; positive regulation of protein localization to cell periphery; positive regulation of protein metabolic process; positive regulation of translation in response to endoplasmic reticulum stress; regulation of presynapse assembly; regulation of translational initiation; translation; translational initiation; cap-dependent translational initiation; regulation of cellular response to stress
Cellular component: cytoplasm; cytoplasmic stress granule; cytosol; eukaryotic translation initiation factor 4F complex; membrane; nucleus; ribosome
Genetic constraint (gnomAD): Loss-of-function variants: 4 observed, 190.8 expected, observed/expected ratio (o/e) 0.021, 90% interval 0.009 to 0.048. The upper end of that interval is the gene's LOEUF score, 0.048, which puts it in group 1 of 6, group 1 being the genes least tolerant of losing a copy. Missense variants: 1,624 observed, 2,140.5 expected, observed/expected ratio (o/e) 0.76, 90% interval 0.73 to 0.79. Synonymous variants: 832 observed, 804.84 expected, observed/expected ratio (o/e) 1.03, 90% interval 0.98 to 1.1.
Homologues: Orthologues: macaque EIF4G1 (99% identical), chimpanzee EIF4G1 (97% identical), rabbit EIF4G1 (95% identical), dog EIF4G1 (95% identical), mouse Eif4g1 (91% identical), pig EIF4G1 (91% identical), rat Eif4g1 (91% identical), guinea pig EIF4G1 (91% identical), rat Eif4g1-ps1 (89% identical), tropical clawed frog eif4g1 (63% identical), zebrafish eif4g1a (57% identical). Paralogues in human: EIF4G3 (48% identical), EIF4G2 (16% identical).
Diseases named in the same sentence as EIF4G1 in open-access papers:
EIF4G1 is named in the same sentence as 109 diseases in open-access papers, as found by Europe PMC text mining. Sharing a sentence is not in itself a finding about the gene and the disease. The quoted sentences say what the papers report.
breast cancer (23 papers, 2012 to 2025). A primary or metastatic malignant neoplasm involving the breast. "Mutation pattern in EIF4G1 in patients with Small lung cancer, cutaneous melanoma, and Breast cancer showed ~ 7.5% alteration frequency." (PMID 31496918, 2019). "The Eukaryotic translation initiation factor 4 gamma 1 (EIF4G1) has been related to breast cancer and Parkinson disease." (PMID 39865125, 2025). "eIF4G1 interactions have been targeted by translation inhibitor 4EGI-1 to reduce eIF4G1-eIF4E interaction in human melanoma and breast cancer cell lines, showing anti-neoplastic activity, which was also confirmed in mice xenograft models." (PMID 39409166, 2024). "Up to date, the expression of EIF4G1 was up‐regulated in nasopharyngeal carcinoma, breast cancer, ovarian cancer and squamous cell lung carcinoma, but there is no report about EIF4G1 being involved in signalling pathways in NSCLC." (PMID 33523588, 2021). "With Breast cancer, 9 to 13% of patients (n = 463 to n = 2509) showed amplification and or up-regulation in EIF4G1." (PMID 31496918, 2019). "For example, inhibiting eIF4G1 delays resolution of DNA double-strand breaks in breast cancer cells by reducing CHK1, CHK2, and BRCA1 levels." (PMID 30382096, 2018). "For example, 4EGI-1, an inhibitor of the interaction between translation initiation factors EIF4E1 and EIF4G1 effectively inhibits breast cancer stem cells (CSCs) through selectively reducing translation persistent in breast CSCs." (PMID 27003362, 2016). "Recent studies have reported that the eukaryotic translation initiation factor 4 gamma 1 (EIF4G1) is related to tumorigenesis and tumor progression in breast cancer." (PMID 27003362, 2016). "In addition, we verified the expression of 3 differential proteins by immunohistochemistry and found that CDH3 and EIF4G1 were significantly higher in breast cancer tissues." (PMID 35787690, 2022). "Poor prognosis was significantly correlated with the high expression of EIF4G1 in breast cancer." (PMID 36551184, 2022). "Among the targets of eIF4G1-mediated translation activation post-IR is BRCA1, a tumor suppressor that facilitates error-free homologous recombination (HR) DSB repair and that causes breast cancer in humans when mutated." (PMID 32932812, 2020). "In addition, recent studies have found that EIF4G1 is overexpressed in a variety of cancers including nasopharyngeal cancer, squamous cell carcinoma and breast cancer." (PMID 27003362, 2016). "CDH3 and EIF4G1 were expressed at significantly higher levels in breast cancer tissues than in paracancerous tissues, but CASP7 was not." (PMID 35787690, 2022). "Similarly, in breast cancer (BC), the inhibition of 5′-tRF-GlyGCC binding to FTO can promote autophagy, which increases the m6A level of eIF4G1 in BC cells and inhibits growth and metastasis." (PMID 39468015, 2024). "We found that eIF4E1 (also named eIF4E), but not eIF4E2, eIF4G1, eIF1A, eIF2α, or eIF5, is significantly increased in BCSCs, in comparison to SKBR-3, MCF-7 and MDA-MB-231 breast cancer cells and non-BCSCs of HMLER (CD44high/CD24low)SA cells." (PMID 25115391, 2014). "Here, we found that translation initiation factor eIF4E1, but not eIF4E2, eIF4G1, eIF1A, eIF2α, or eIF5, is significantly enhanced in breast CSCs in comparison to non-CSC breast cancer cells." (PMID 25115391, 2014).
Parkinson disease (16 papers, 2012 to 2024). A progressive degenerative disorder of the central nervous system characterized by loss of dopamine producing neurons in the substantia nigra and the presence of Lewy bodies in the substantia nigra and locus coeruleus. "The eIF4G1 has been found to have five Parkinson’s disease-associated mutations: Ala502Val; Gly686Cys; Ser1164Arg; Arg1197Trp; and Arg1205His." (PMID 30841624, 2019). "Eukaryotic translation initiation factor 4-gamma 1 (EIF4G1) gene mutations have recently been reported in autosomal dominant, late-onset Parkinson’s disease (LOPD)." (PMID 23617574, 2013). "The aim of this study was to investigate EIF4G1 parkinsonism-related variants in two separate cohorts and study coding variability across the gene." (PMID 22561553, 2012). "Chartier-Harlin and colleagues recently reported mutations in the eukaryotic translation initiation factor 4-gamma (EIF4G1) gene in families with parkinsonism." (PMID 22561553, 2012). "At least 19 genetic loci for Parkinsonism have been identified to date, ten of which are autosomal dominant genes: SNCA (PARK1/PARK4), PARK3, UCHL1 (PARK5), LRRK2 (PARK8), GIGYF2 (PARK11), HTRA2 (PARK13), VPS35 (PARK17), EIF4G1 (PARK18), TMEM230 (PARK21), and CHCHD2 (PARK22)." (PMID 34356877, 2021).
viral infection (16 papers, 2004 to 2025). "Since eIF4G1 levels were not affected by the expression of the NS3 protease, we assessed whether the eIF4G1 protein is cleaved or degraded during virus infection using ZIKV infected and mock-infected 293T and A549 cells." (PMID 34207340, 2021).
melanoma (14 papers, 2002 to 2025). A malignant, usually aggressive tumor composed of atypical, neoplastic melanocytes. "EIF4G1 gene mutations promote melanoma cell proliferation by affecting mRNA translation." (PMID 40860809, 2025). "Compared to that in HeLa and SUM149 cells, PVSRIPO translation in A375 (melanoma) and T3M4 (pancreatic ductal adenocarcinoma) cells was delayed and eIF4G1 cleavage was inefficient." (PMID 33849973, 2021). "Another small molecule SBI-0640756 (SBI-756), a first-in-class inhibitor that targets EIF4G1 and disrupts the EIF4F complex, can effectively inhibit the growth of NRAS, BRAF, and NF1-mutant melanomas in vitro and delay the onset and reduce the incidence of Nras/Ink4a melanomas in vivo." (PMID 27003362, 2016).
lung carcinoma (12 papers, 2010 to 2025). "Our previous study reported that EIF4G1 was significantly up‐regulated in NSCLC cell lines compared to normal lung cells, which makes these lung cancer cells more susceptible to EIF4G1‐targeted therapy." (PMID 33539648, 2021). "Interestingly, among the top 6 co-expressed genes of PSMD2, the EIF4G1 and TUBA1C were reported to be related to immune infiltration in lung cancer, and EIF4G1 is significantly associated with the PD-L1 expression." (PMID 36505799, 2022). "The results demonstrated that EIF4G1 promoted the G1/S transition of the cell cycle and tumour cell proliferation in non‐small cell lung cancer." (PMID 33523588, 2021). "Lung cancer patients (n = 178 to n = 1144) showed a range of 14 to 59% of amplification and or up-regulation in EIF4G1 for different datasets." (PMID 31496918, 2019). "In a variety of cancers, including NPC, lung cancer, and breast cancer, the expression levels of EIF4G1 are significantly up-regulated." (PMID 20398343, 2010). "In addition, frequent amplification of EIF4G1 on chromosome 3q27.1 and over-expression of EI4G1 mRNA was also displayed in lung cancer and hypopharyngeal cancer, which suggest the involvement of EIF4G1 in tumorigenesis." (PMID 20398343, 2010). "In the current study, we found that EIF4G1 is required for NSCLC cell survival and proliferation, and it also acts as an oncoprotein to promote lung cancer cell malignant behaviors." (PMID 27003362, 2016). "We also tested the functional role of EIF4G1 in other malignant behaviors of NSCLC cells such as migration and invasion, which are important to lung cancer development and metastasis." (PMID 27003362, 2016). "Finally, EIF4G1 displays diverse interactions in LUSC, linking with LUAD-related ZFHX4, COL6A6, and unusual PLPPR3 connections to lung cancer genes." (PMID 38389572, 2024). "YTHDC2 was shown to form complexes with eukaryotic translation initiation factor 4 gamma 1 (eIF4GI) and bind to the m6A methylation site of the vascular endothelial growth factor A (VEGFA) 5’UTR, thereby promoting its translation and accelerating lung cancer angiogenesis." (PMID 38790013, 2024). "Eukaryotic translation initiation factor 4 gamma 1 (EIF4G1), as the key component of the transcription initiation factor complex EIF4F, is significantly upregulated in multiple solid tumours, including lung cancer." (PMID 33523588, 2021). "Taken together, these results have for the first time demonstrated the immunoregulatory functions, clinical relevance and therapeutic potential of the EIF4G1 network in NSCLC, which may represent a promising and novel target to improve lung cancer treatment." (PMID 33539648, 2021). "Together, our results indicate that EIF4G1 functions as an oncoprotein during NSCLC development, which may represent a novel and promising therapeutic target in lung cancer." (PMID 27003362, 2016).
prostate carcinoma (11 papers, 2015 to 2025). A carcinoma that arises from epithelial cells of the prostate gland. "Recent studies suggest that high expression of EIF4G1 is associated with poor prognosis of pancreatic ductal adenocarcinoma and prostate cancer and may serve as a novel prognostic biomarker." (PMID 35787690, 2022). "UCA1 enhances eIF4G1 levels via sponging miR-331-3p, while knockingdown of UCA1 sensitizes prostate cancer cells to radiotherapy by suppressing eIF4G1 expression via miR-331-3p/eIF4G1 axis." (PMID 33672592, 2021). "We discovered that alteration frequency in EIF4G1 is prevalent in human cancers e.g. prostate cancer (~ 25%), ovarian cancer (~ 15%), Head and Neck cancer (~ 13%) and cervical cancer (~ 12.5%)." (PMID 31496918, 2019). "We observed that amplification of EIF4G1 were prominent in prostate cancer (~ 25%), ovarian cancer (~ 15%), Head and neck cancer (~ 13%) and cervical cancer (~ 12.5%)." (PMID 31496918, 2019). "In the present study, we evaluated the expression of eIF4G1 in prostate cancer samples, analyzed eIF4G1 expression in multiple prostate cancer cohorts and investigated the functional role of eIF4G1 using cell culture model systems." (PMID 29748619, 2018). "EIF4G1 was also notable in that it was the only gene altered at the protein level in 14% of TCGA prostate cancer samples tested, measured by reverse-phase protein arrays (RPPA), which suggests it may be a useful histological biomarker." (PMID 26501111, 2015). "We recently observed that EIF4G1 is overexpressed/amplified in the majority of patients with castration-resistant prostate cancer (CRPC), and plays an essential role in prostate cancer progression, cell growth and metastasis." (PMID 31496918, 2019). "In prostate cancer, lncRNA UCA1 levels were found to be positively correlated with eIF4G1 levels." (PMID 33672592, 2021). "However, the role of eIF4G1 has not been evaluated in Prostate Cancer (PCa)." (PMID 29748619, 2018).
nasopharyngeal carcinoma (9 papers, 2010 to 2024). A carcinoma arising from the nasopharyngeal epithelium. "High expression of EIF4G1 has been found in various tumors and is associated with poor prognosis, including breast, lung, hypopharyngeal, and nasopharyngeal cancers, which is consistent with our findings." (PMID 35787690, 2022). "Overexpression of EIF4G1 is associated with tumor progression and poor prognosis in nasopharyngeal carcinoma." (PMID 31967976, 2020). "The authors found that the expression level of EIF4G1 mRNA in nasopharyngeal carcinoma tissues and cell lines was significantly higher than that in normal nasopharyngeal tissues and NP69 cells." (PMID 38405671, 2024). "The aim of the present study was to analyze the expression of eukaryotic translation initiation factor 4 gamma 1 (EIF4G1) in nasopharyngeal carcinoma (NPC) and its correlation with clinicopathologic features, including patients' survival time." (PMID 20398343, 2010). "Another report showed that EIF4G1 could be a biomarker for the prognosis of patients with nasopharyngeal carcinoma." (PMID 38405671, 2024).
autism (5 papers, 2017 to 2026). Persistent deficits in social interaction and communication and interaction as well as a markedly restricted repertoire of activity and interest as well as repetitive patterns of behavior. "Pharmacologically inhibiting the interaction between eIF4G1/eIF4E suppressed translation and has been used to affect spine morphology in autism mouse models." (PMID 40931164, 2026). "Accordingly, mutations in EIF4G1 have been recognized to associate with PD, and deregulation of EIF4E activity seems to increase susceptibility to autism (AUTS19)." (PMID 28798667, 2017). "Mutations in the genes encoding various factors that regulate translation (eIF4E, eIF4G1, GRB10‐interacting GYF protein 1 (GIGYF1), GIGYF2, and zinc finger protein 598) were identified in people with autism (Simons Foundation Autism Research Initiative, SFARI database)." (PMID 41236931, 2025). "MEs within the EIF4G1 and EIF4G3 transcripts were shown to be misregulated in autism patients and control synaptic translation and cognition contributing to pathogenesis of this condition." (PMID 33207694, 2020).
neuroblastoma (5 papers, 2013 to 2025). Neuroblastoma (NB) is the most common solid, extracranial childhood tumor. "Interestingly, six genes ARMC6, DCTPP1, EIF4G1, ELOVL6, FBL and PRMT1 were associated with the clinical overall survival of neuroblastoma in both TARGET and GSE85047 datasets." (PMID 32593299, 2020). "Neuroblastoma patients with MYCN amplification and high EIF4G1 expression demonstrated worse clinical outcomes in TARGET dataset." (PMID 32593299, 2020). "So, we tested the combinational prognostic effects of EIF4G1 expression and MYCN amplification in patients with neuroblastoma." (PMID 32593299, 2020). "The present study suggested new prognostic markers of ARMC6, DCTPP1, EIF4G1, ELOVL6 and FBL in neuroblastoma and highlighted the combinational prognostic significance of MYCN amplification and EIF4G1 expression in patients with neuroblastoma." (PMID 32593299, 2020). "Neuroblastoma patients were divided into four sub-groups based on MYCN status and EIF4G1 mean expression level in TARGET and GSE85047 datasets." (PMID 32593299, 2020). "EIF4G1 stood out as another interesting candidate driver in AML and lymphoid entities, supported by previous analyses suggesting that EIF4G1 is involved in cell survival in AML as a downstream target of MYCN, a known oncogene in neuroblastoma." (PMID 38769532, 2024). "Therefore, functions and prognosis of ARMC6, DCTPP1, EIF4G1, ELOVL6 and FBL in neuroblastoma should be further studied." (PMID 32593299, 2020). "In GSE85047 dataset, neuroblastoma patients without MYCN amplification were divided into EIF4G1 highly expressed group and EIF4G1 lowly expressed group." (PMID 32593299, 2020). "We found that neuroblastoma patients without MYCN amplification and with low EIF4G1 expression had best prognosis." (PMID 32593299, 2020). "And neuroblastoma patients without MYCN amplification and low EIF4G1 expression had best prognosis." (PMID 32593299, 2020). "However, the functions and prognosis of ARMC6, DCTPP1, EIF4G1, ELOVL6 and FBL in neuroblastoma were not reported." (PMID 32593299, 2020). "Neuroblastoma patients without MYCN amplification and low EIF4G1 expression had best prognosis." (PMID 32593299, 2020).